MIR320A (microRNA 320a)
Synonyms: hsa-mir-320; MIRN320; MIRN320A; hsa-mir-320a; mir-320a
Gene: MicroRNA gene on chromosome 8 (22,244,962 to 22,245,043, reverse strand). Ensembl gene ENSG00000208037.
Gene Ontology:
Biological process: cellular response to glucose stimulus; long-term synaptic potentiation; miRNA-mediated post-transcriptional gene silencing; negative regulation of gene expression; positive regulation of stem cell proliferation
Cellular component: RISC complex
Homologues: Orthologues: chimpanzee ptr-mir-320a (99% identical), macaque mml-mir-320a (94% identical), rat Mir320a (93% identical), dog MIR320A (90% identical), guinea pig MIR320A (90% identical), pig ssc-mir-320 (89% identical), tropical clawed frog xtr-mir-320 (34% identical). Paralogues in human: MIR320B2 (68% identical), MIR320B1 (61% identical), MIR320E (59% identical), MIR320C2 (54% identical), MIR320D2 (52% identical).
Diseases named in the same sentence as MIR320A in open-access papers:
MIR320A is named in the same sentence as 4 diseases in open-access papers, as found by Europe PMC text mining. Sharing a sentence is not in itself a finding about the gene and the disease. The quoted sentences say what the papers report.
prostate carcinoma (1 paper, 2016). A carcinoma that arises from epithelial cells of the prostate gland. "Mir320a acts as a tumour suppressor in different cancer types and its downregulation correlates with chemoresistance in colon, breast and prostate cancer." (PMID 27816966, 2016).
type 2 diabetes (1 paper, 2024). "A possible trend toward significance was found in the expression of the MIR126 gene (p = 0.051), the MIR133A1 gene (p = 0.076), the MIR143 gene (p = 0.08), and the MIR320A gene (p = 0.095) in patients with type 2 diabetes." (PMID 38256676, 2024).
MIR320A also shares sentences with these, for which no sentence is quoted: tumor (2 papers); cancer (1).